MTOR (mechanistic target of rapamycin kinase)
Diseases named in the same sentence as MTOR in open-access papers (continued):
Sharing a sentence is not in itself a finding about the gene and the disease.
gastric cancer (continued). "FAK/Akt/mTOR also seems to be the focus of research in gastric cancer, and many molecules are involved in this pathway, promoting gastric cancer growth and migration." (PMID 36407100, 2022). "In SGC-7901 and MGC-803 gastric cancer cells, St-inhibited viability and proliferation and induced autophagy by blocking the Akt/mTOR pathway, with autophagy playing a cryoprotective role against apoptosis induced by St." (PMID 36234962, 2022). "NK cell activity is decreased in gastric cancer, and gastric cancer mesenchymal stem cells promote tumor growth and inhibit NK cell function through the mTOR signaling pathway." (PMID 35463631, 2022). "For gastrointestinal cancers, BBR enhanced chemosensitivity to irinotecan via inhibition of NF-κB in colon cancer, and improved chemosensitivity to Cisplatin by enhancing cell apoptosis and repressing PI3K-AKt/mTOR signaling in gastric cancer." (PMID 36297310, 2022). "In the present study, TAMs-derived CXCL5 was demonstrated to promote 5-FU-resistance and enhance the ability of anti-apoptosis of gastric cancer cells through the activation of PI3K/AKT/mTOR pathway, which has been shown to involve in cancer progression." (PMID 36151545, 2022). "Supra-physiological doses of CAR are found to inactivate mTOR signaling in human gastric carcinoma cells." (PMID 36671729, 2022). "Carnosine has been shown to inhibit the proliferation of human gastric carcinoma cells by regulating Akt and mammalian target of rapamycin (mTOR) signaling." (PMID 34976156, 2022). "We also proved that the anti-MUC1 antibody with OM-86II decreased the concentrations of MMP-9, sICAM1 and mTOR in gastric cancer cells." (PMID 34770912, 2021). "Circ-NRIP1 has been shown to act as a miR-149-5p sponge, thereby suppressing autophagy through the AKT1/mTOR pathway, promoting gastric cancer (GC) cell proliferation and altered energy metabolism." (PMID 35008183, 2021). "TMPO.AS1 performs its tumor-promoting function via activating the PI3K/AKT/mTOR pathway in gastric cancer and HCC." (PMID 34745939, 2021). "APOC2 cooperates with CD36 to regulate EMT process via PI3K/AKT/mTOR signaling, which eventually promotes tumor progression and peritoneal metastasis in gastric cancer." (PMID 34459127, 2021). "A study indicates that miR-21 is a potential tumor marker for gastric cancer, and another reveals that miR-101-2, miR-125b-2 and miR-451a are potential suppressors for gastric cancer via regulating PI3K/Akt/mTOR pathway." (PMID 33883305, 2021). "For example, the STAT3/c-Myc axis regulates the energy metabolism of gastric cancer cells by synergistically communicating with the mTOR/PKM2 pathway." (PMID 34608390, 2021). "Narciclasine can induce autophagy-dependent apoptosis in gastric cancer cells by inhibiting the phosphorylation level of Akt/mTOR and thus reduce the proliferation of gastric cancer cells." (PMID 34753517, 2021). "In conclusion, miR-496 inhibited the proliferation through the AKT/mTOR signaling pathway via targeting LYN in gastric cancer cells." (PMID 34514167, 2021). "Frequent activation of mTOR signaling in trastuzumab-resistant NCI N87 (T-R) HER2 + gastric cancer cells identified by a parallel quantitative proteomics profiling suggested the need of an mTOR antagonist for the T-R HER + gastric cancers." (PMID 34540820, 2021). "Many studies have reported overactivation of the PI3K/AKT/mTOR pathway and high levels of phosphorylated/activated Akt in gastric cancer." (PMID 33800129, 2021). "It is possible that LIT3527 regulates gastric cancer cell survival and migration through modulating mTOR signaling." (PMID 34234860, 2021). "Its potential mechanism is to inhibit phosphorylation of the Akt/mTOR signaling pathway and activate autophagy, thus promoting apoptosis of gastric cancer cells." (PMID 34753517, 2021).
gastric cancer (continued). "Studies have shown that the PI3K/AKT/mTOR pathway is involved in regulating the occurrence and development of gastric cancer mediated by cell proliferation, antiapoptosis, migration, and glucose metabolism." (PMID 34853601, 2021). "It has also been shown to induce apoptosis in human gastric cancer cells by activating the protein kinase B/mammalian target of rapamycin (Akt/mTOR) signaling pathway." (PMID 34900710, 2021). "In our study, inhibition of phosphorylated Akt or mTOR by specific inhibitor MK-2206 reinforced SS-induced apoptosis and autophagy in gastric cancer cells." (PMID 33708631, 2021). "Syringic acid suppressed gastric cancer cell proliferation, inflammation, and induced apoptosis by upregulating mTOR via AKT signaling pathway." (PMID 34970579, 2021). "The correlation of Akt/mTOR with levobupivacaine in modulating ferroptosis of gastric cancer cells needs to verify in future investigations." (PMID 34177591, 2021). "Studies have found that gastric cancer cells showed periodic mutations in some key oncogenes such as Her2, epidermal growth factor receptor (EGFR), PI3K, mTOR, or c-Met15." (PMID 34326374, 2021). "PI3Kγ expression on macrophages suppresses the immune responses during the growth of gastric cancer through the stimulation of Akt, mTOR, and C/EBPβ and inhibition of NFκB and eventually increases the numbers of metastatic nodules in the lung." (PMID 32902664, 2021). "In conclusion, miR-496 inhibits the proliferation and metastasis and induces the apoptosis through targeting LYN and inhibiting the AKT/mTOR signaling pathway in gastric cancer." (PMID 34514167, 2021). "In the present study, we investigated the relationship between the TNFAIP8 and the mTOR‐Akt‐ULK1signalling pathway as well as its role in gastric cancer." (PMID 33682317, 2021). "To further demonstrate the role of Akt/mTOR dephosphorylation in narciclasine-induced autophagy, we treated gastric cancer cells with insulin (Akt activator) to reactivate Akt/mTOR signaling pathway." (PMID 34753517, 2021). "For example, GAS5/miR-106a-5p/Akt/mTOR (mammalian target of rapamycin) has been reported in gastric cancer." (PMID 33391419, 2021). "OGFRP1 knockdown blocks cell proliferation and migration, and it induces cell cycle arrest and apoptosis by inhibiting the activity of the AKT/mTOR pathway in human gastric cancer." (PMID 33744848, 2021). "Everolimus, as an mTOR inhibitor used in clinic, is active and well-tolerated in gastric cancer patients with chemotherapy-refractory metastasis." (PMID 34234860, 2021). "Rui Peng and colleagues found that activation of the AMPK/mTOR signaling pathway induced survival autophagy to resist drug therapy in FGFR-TKI resistant gastric cancer cell lines." (PMID 33568192, 2021). "To elucidate the underlying mechanism of SS-mediated autophagy and apoptosis in gastric cancer cells; we examined the level of phosphorylation of Akt and mTOR by western blot." (PMID 33708631, 2021). "The experiments showed the overexpression of AKT1 and MTOR genes in gastric mucosa of gastric cancer patients and showed that they play vital roles in cell growth, proliferation, metabolism, angiogenesis, and survival in mediating cellular functions." (PMID 34899944, 2021). "The phosphorylated mTOR (p-mTOR) is a prognostic marker which occurs in the downstream processing of the PI3K/AKT/mTOR pathway in gastric cancer." (PMID 34970579, 2021). "In conclusion, carnosic acid exhibits antitumor activity against human gastric cancer cells via modulating the Akt-mTOR signaling pathway that plays a crucial role in gastric cancer cell proliferation and survival." (PMID 33800129, 2021). "PB2 inhibits viability and promotes apoptosis and autophagy of gastric cancer cells through Akt/mTOR signaling pathway." (PMID 33627124, 2021). "Our results showed that Akt/mTOR signaling is also a regulated pathway by PB2 in gastric cancer, as evidenced by decreased expression of p-Akt and p-mTOR in PB2-indeuced SGC-7901 cells." (PMID 33627124, 2021).
gastric cancer (continued). "The results of our in vitro studies indicate that the natural compound narciclasine can mediate autophagy-dependent apoptosis of gastric cancer cells by inhibiting the phosphorylation level of Akt/mTOR." (PMID 34753517, 2021). "In line with this, activation of the Akt/mTOR signaling pathway has been reported to induce drug resistance and promote proliferation and migration of gastric cancer cells." (PMID 34540820, 2021). "In order to explore the role of Akt/mTOR pathway in PB2- in cell viability reduction induced by PB2 in gastric cancer cell, Akt inhibitor LY294002 was applied." (PMID 33627124, 2021). "In another study, treatment of human gastric cancer cells with AUR induced apoptosis via suppression of the mTOR pathway." (PMID 35432798, 2021). "PI3K-Akt-mTOR signaling pathway is frequently activated in gastric cancer patients, and can promote the release of free Bcl-2 from Bcl-2/Bcl-xl dimer, and promote the proliferation and growth of tumor." (PMID 33627124, 2021). "Mesenchymal stem cells secreted IL-8 which in turn activated STAT3 and mTOR (mammalian target of rapamycin), to induce c-Myc and PD-L1 expressions in gastric cancer cells." (PMID 34503236, 2021). "The PI3K/Akt/mTOR pathway is known to be commonly upregulated in various cancers, including gastric cancer." (PMID 33800129, 2021). "Considering the functions of LIT3527 in apoptosis and autophagy of gastric cancer cells, we analyzed several pathways and found that mTOR pathway was involved." (PMID 34234860, 2021). "Our study is the first report on the anti-cancer effects of syringic acid against gastric cancer cells via apoptosis, inhibition of inflammation, and the suppression of the mTOR/AKT signaling pathway." (PMID 34970579, 2021). "So, the PI3K/AKT/mTOR signaling pathway was investigated to further elucidate the mechanism of BBD in reversing the MDR of the gastric cancer cell." (PMID 34306145, 2021). "In trastuzumab-resistant HER2 positive gastric cancer cells, mTOR pathway is among multiple signaling pathways that mediate trastuzumab resistance." (PMID 33976744, 2021). "Activated growth-promoting pathways in gastric cancer include Wnt, Akt/mTOR and mitogen-activated protein kinase (MAPK) pathways." (PMID 34659579, 2021). "LncRNA NORAD inhibited apoptosis and promoted proliferation of gastric cancer cells by inhibiting miR-214 expression and activating Akt/mTOR pathway." (PMID 34234860, 2021). "In vitro and in vivo experimentations revealed the inhibitory potential of BBR in the gastric cancer cell line BGC-823 due to the induction of cytostatic autophagy through suppression of MAPK/mTOR/p70S6K and Akt signaling pathways." (PMID 34885950, 2021). "This study showed that PB2 decreases the expressions of p-Akt and p-mTOR in gastric cancer cells, and similar results were also observed in colorectal cancer cells from other report." (PMID 33627124, 2021). "The introduction of syringic acid to gastric cancer cells mainly inhibited the development of inflammatory mediators via regulation of the AKT/mTOR signaling pathway." (PMID 34970579, 2021). "Recent reports suggest that quercetin activates autophagy through mechanistic target of rapamycin (mTOR) or signal transducer and activator of transcription 3 signaling in gastric cancer, ovarian cancer, and effusion lymphoma cells." (PMID 34195429, 2021). "More importantly, mTOR has been reported to be the target of miR-101-3p in gastric cancer and vascular endothelial cells." (PMID 33336000, 2020). "In this study, we report that 2,6-DMBQ reduces the growth of gastric cancer by targeting mTOR in vitro and in vivo." (PMID 32517736, 2020). "The results of signaling pathway and in vitro kinase assay strongly support that 2,6-DMBQ is a potent mTOR protein kinase inhibitor and can reduce mTOR signaling pathway in gastric cancer cells." (PMID 32517736, 2020).
gastric cancer (continued). "Knockdown or inhibition of TTK in gastric cancer cells resulted in Akt‐mTOR dysregulation and enhanced apoptosis of cancer cells." (PMID 32530571, 2020). "Recent research has shown the PI3K/AKT/mTOR pathway to be activated in gastric cancer and that activation of this pathway correlated with metastasis, poor prognosis, and reduced survival of gastric cancer patients." (PMID 32076440, 2020). "For instance, circNRIP1 was proven to modulate the autophagy and cancer cell metabolism switch into the Warburg effect by alteration of AKT1 expression and, consequently, the AKT/mTOR pathway, which induces tumor development and metastasis in gastric cancer." (PMID 33194736, 2020). "Our results indicate that TSPAN9 promotes autophagy and enhances the resistance of gastric cancer cells to 5-FU by inhibiting the activation of PI3K–Akt–mTOR signaling." (PMID 31911756, 2020). "We next examined the effect of mTOR knockdown on anchorage-dependent or -independent growth of gastric cancer cells." (PMID 32517736, 2020). "To determine the influence of mTOR knockdown on gastric cancer cell growth, we established cells stably expressing knockdown of mTOR or a control shRNA and determined the expression of mTOR protein by Western blotting." (PMID 32517736, 2020). "Our data confirm that BAG2 can regulate the proliferation of gastric cancer cells by activating AKT/mTOR pathway." (PMID 32082999, 2020). "In the present study, we demonstrated that NUCKS plays an oncogenic role in gastric cancer via an mTOR-mediated signaling pathway." (PMID 32958058, 2020). "PI3K/Akt/mTOR signaling axis has been regarded as an important pathway in regulating drug-resistance in different cancer types including gastric cancer." (PMID 33362566, 2020). "IL-8 has been characterized to activate PI3K-Akt signaling through modulating phosphorylation/activation of Akt and S6, while PI3K-Akt-mTOR signaling was also reported to enhance IL-8 production as feedback, which comply with our findings in gastric cancer." (PMID 31912229, 2020). "For instance, miR-7 is a tumor suppressor and increase cisplatin sensitivity of gastric cancer cells by targeting mTOR, indicating its potential application for the treatment of human gastric cancer in the future." (PMID 31959187, 2020). "LncRNAs regulate some classical signalling pathways, such as Notch, mTOR and NF‐κB, and many abnormally expressed LncRNAs are of clinical significance for the diagnosis of gastric cancer." (PMID 33145980, 2020). "To determine the levels of mTOR and p70S6K protein expression in gastric cancer cells, we performed Western blotting using 4 gastric cancer cell lines." (PMID 32517736, 2020). "Recent studies have shown that the PI3K/AKT/mTOR pathway was activated in gastric cancer and that activation of this pathway was correlated with metastasis, poor prognosis and lower survival in gastric cancer patients." (PMID 31904088, 2020). "Lactobacillus casei extracts induce apoptosis of gastric cancer cells through NF-κB and mTOR-mediated signaling." (PMID 32238777, 2020). "Circ_RNA circNRIP1 can sponge miRNA-149-5p to promote gastric cancer progression via regulating AKT1/mTOR signaling." (PMID 33598424, 2020). "We also evaluated the effect of leaf extracts from MeJA-treated plants on the expression of proteins related to gastric cancer (AKT/mTOR and mitogen-activating protein kinases (MAPK) signaling pathways)." (PMID 31948009, 2020). "The CXCR4/mTOR signaling pathway is also thought to play a role in promoting migration and inducing autophagic cell death in the peritoneal diffusion of gastric cancer cells." (PMID 32477008, 2020). "Dual inhibitor of PI3K and mTOR (NVP-BEZ235) promoted the drug resistance of gastric cancer cells to 5-fluorouracil." (PMID 33362566, 2020). "The results showed that anchorage-dependent and -independent growth of gastric cancer cells was significantly reduced by knockdown of mTOR." (PMID 32517736, 2020).
gastric cancer (continued). "Studies have also found that metastasis associated with colon cancer 1 (MACC1) regulates PDL1 expression and tumor immunity in gastric cancer (GC) cells through the c-Met/AKT/mTOR pathway." (PMID 32863765, 2020). "Previously, phosphorylated mTOR was found to be significantly over-expressed and correlated with various clinical and pathologic parameters in patients with gastric cancer." (PMID 32517736, 2020). "Flavokawain B, a chalcone, induces autophagic cell death in gastric cancer cells via induction of ROS, mTOR pathway inhibition, and upregulation of LC3-II accumulation." (PMID 33415148, 2020). "In conclusion, our findings demonstrate that 2,6-DMBQ is a potent mTOR inhibitor that reduces growth of gastric cancer." (PMID 32517736, 2020). "Many studies have shown that the overexpression of mTOR is common in gastric cancer and that p-mTOR is suggested to be an independent prognostic factor for gastric cancer." (PMID 32041519, 2020). "TSPAN9 enhance the resistance of gastric cancer to 5-fluorouracil by activating PI3K/AKT/mTOR-mediated autophagy." (PMID 33362566, 2020). "In the present study, we report that 2,6-DMBQ is a novel mTOR inhibitor that reduces gastric cancer growth in vitro and in vivo." (PMID 32517736, 2020). "For instance, circNRIP1 aggravates gastric cancer progression by sponging microRNA-149-5p via the AKT1/mTOR pathway." (PMID 32831141, 2020). "PI3K/Akt/mTOR pathway aberrant is common in gastric carcinoma which regulates tumor occurence and progression, such as those in proliferation and in apoptosis." (PMID 32109290, 2020). "The results of luciferase assays indicated that mTOR was a direct target of miR-224-5p, which is consistent with a previous study of miR-224-5p in a gastric cancer cell." (PMID 31179240, 2019). "Taken together, our findings conclude the GAS5 overexpression suppresses tumorigenesis and development of gastric cancer by sponging miR-106a-5p through the Akt/mTOR pathway." (PMID 31182630, 2019). "Quantification proteomics analysis revealed that the differentially expressed proteins in gastric cancer cells were mainly involved in the AKT/mTOR and MEK/ERK signalling pathways." (PMID 31139014, 2019). "PP242 (Tokinib) is another selective ATP-competitive inhibitor of mTOR that has a promising anti-cancer activity over several cancer types, such as leukemia, gastric cancer, and colon cancer." (PMID 31277692, 2019). "Aberrant activation of phosphatidylinositol-3 kinases (PI3K)/AKT/mTOR (mammalian target of rapamycin) pathway is a critical event during gastric cancer progression." (PMID 29704890, 2019). "Researches demonstrated that PIK3CA, PIK3CB, AKT1 and mTOR are overexpressed in GC cell lines, and mTOR pathway is active in almost 60% of gastric cancer patients." (PMID 30754640, 2019). "It has been reported that CXCR4 was involved in mTOR-dependent migration of gastric carcinoma cells." (PMID 31882811, 2019). "GRINA knockdown decreased PI3K/Akt/mTOR signaling and glycolytic metabolism in gastric cancer cells." (PMID 30541591, 2018). "Our findings exhibit that PEC inhibits the viability of human gastric cancer cells through inactivation of proteasome-dependent degradation of Akt/PI3K/mTOR pathway." (PMID 30096805, 2018). "ADAMTS-9 acts as a functional tumor suppressor in gastric cancer through inhibiting the oncogenic AKT/mammalian target of rapamycin (mTOR) signaling pathway and ADAMTS-9 is related to beta cell function in type 2 diabetes." (PMID 29393911, 2018). "Our results show that the PI3K/AKT/mTOR pathway plays a vital role in PEC induced cell death in human gastric cancer cell." (PMID 30096805, 2018). "In the present study, PEC significantly decreased the expression levels of p-PI3K, p-AKT (Ser473), which led to down-regulation of p-mTOR, showing the ability of PEC to inhibit the hyperactivated PI3K/AKT/mTOR in human gastric cancer cells." (PMID 30096805, 2018).